APOE (apolipoprotein E)
Diseases named in the same sentence as APOE in open-access papers (continued):
Sharing a sentence is not in itself a finding about the gene and the disease.
prostate carcinoma (continued). "Apolipoprotein E gene was shown to regulate aggressive behaviors in prostate cancer cells by deregulating cholesterol homeostasis." (PMID 35453307, 2022). "ApoE was highly expressed in the PC-3 human prostate cancer cell line, and its expression was directly correlated with the Gleason score of prostate cancer tissues, hormone independence, and local and distant metastasis." (PMID 35892323, 2022). "As cholesterol is known to be a potential target for CRPC, ApoE has been suggested to play a potential role in prostate cancer progression." (PMID 31396486, 2019). "Currently, there are no clearly defined mechanisms to explain the relationship between the ApoE isoforms, especially the ApoE2/E4 phenotype and aggressive prostate cancer." (PMID 23934233, 2013). "Our results showed a relationship between specific ApoE isoforms and the level of expression of cav-1 mRNA in prostate cancer cell lines." (PMID 23934233, 2013). "For example, APOE is elevated in prostate cancers and correlates with a poor prognosis." (PMID 39990672, 2025). "Based on these findings, it is hypothesized that M2 macrophages in prostate cancer release APOE, contributing to the regulation of the tumor microenvironment." (PMID 38349474, 2024). "It has been shown that nanoparticles modified with apolipoprotein E, or carrying it as part of a protein corona, are capable of penetrating into various tissues, such as a human prostate cancer cell line (PC3), a mouse brain endothelioma cell line (bEnd3), and mouse brain cells." (PMID 39513847, 2024). "Additionally, in prostate cancer, it has been observed that the secretion of ApoE can regulate the phenotype of neutrophils, promoting an immunosuppressive function." (PMID 39695088, 2024). "Additionally, in prostate cancer, tumor-secreted APOE can bind to TREM2 on neutrophils, promoting neutrophil senescence." (PMID 39497214, 2024). "APOE has also been studied in prostate cancer and expression varies with the Gleason score, suggesting that APOE expression may represent a marker of more aggressive tumors." (PMID 25428203, 2014). "However, all the clonal macrophage cell lines used in that study carried three different homozygous ApoE-isoforms, whereas our investigated prostate cancer cell lines had a combination of heterozygous and homozygous ApoE isoforms." (PMID 23934233, 2013). "Immunohistochemical information from the HPA database showed that higher staining of GSTM4, PLP1, and PTGS2 was found in normal prostate tissue, while higher staining of SLC27A2, SLC45A3, APOE, and ABCC4 was observed in prostate cancer tissue." (PMID 40861808, 2025). "ApoE and TREM2 expression are increased in prostate cancer and correlate with poor prognosis." (PMID 41465180, 2025). "Additionally, in the tumor microenvironment of cribriform prostate cancer, there was found to be an increase in the number of C1QB+ TREM2+ APOE+ macrophages." (PMID 40242752, 2025). "For example, tumor-derived APOE induced senescence of TRME and NEU cells, and that the removal of senescent cells neu by HDAC inhibitors could improve the therapeutic efficacy of prostate cancer treatment." (PMID 40292294, 2025). "Data from the HPA database also showed positive APOE expression in prostate cancer, with no protein expression in normal prostate tissue." (PMID 38349474, 2024). "Although we are not aware of such a relationship in prostate cancer cell lines, the concept is consistent with our findings that the three ApoE phenotypes in our prostate cancer cell lines have distinct abilities to promote cholesterol efflux, and to inversely accumulate cholesterol." (PMID 23934233, 2013). "Recent studies have demonstrated significantly lower levels of serum APOA and APOE in BPH patients compared to controls, while levels were notably higher in BPH than in prostate cancer patients." (PMID 38136890, 2023).
delirium (36 papers, 2011 to 2026). A disorder characterized by confusion; inattentiveness; disorientation; illusions; hallucinations; agitation; and in some instances autonomic nervous system overactivity. "Variants at the APOE gene and within its close genomic region on chromosome 19 were significantly associated with delirium." (PMID 41286463, 2026). "Genetic variants on the APOE gene on chromosome 19 were identified as significantly associated with delirium, with the top variant hit, rs429358, showing population-specific association patterns." (PMID 41286463, 2026). "Variants in the APOE genomic region that were significant in our delirium GWAMA were also significant in MTAG." (PMID 41286463, 2026). "Meta-analyses indicate that APOE ε4 carriers exhibit approximately twice the risk of developing delirium in patients following major surgery, particularly orthopedic and cardiac procedures, compared to non-carriers (pooled OR 1.89, 95% CI 1.36–2.62)." (PMID 41375722, 2025). "Other studies have also investigated the associations between plasma markers of inflammation, coagulation, brain injury, and delirium duration in elderly hospitalized patients and the interaction between APOE ε4 allele and vitamin D variations." (PMID 37159618, 2023). "In the analysis of genetic predictors in PD only, the MAPT H1/H1 haplotype was associated with increased risk of delirium (HR 2.08, 95% CI 1.08–4.00) and APOE ε4 carrier status was associated with increased risk of delirium (HR 2.16, 95% CI 1.15–4.08)." (PMID 34635668, 2021). "Participants with one or more APOE ε4 allele were at a substantial increased risk of incident delirium." (PMID 30770424, 2019). "The carriers of APOE ε4 allele have greater risk of delirium development and are more predisposed to cellular damage within the brain." (PMID 26106326, 2015). "The APOE ε4 allele was found to be correlated with longer duration of delirium in mechanically ventilated critically ill patients." (PMID 26106326, 2015). "To assess this hypothesis, we tested whether the interaction term between each plasma protein level and APOE-ε4 status significantly associated with incident delirium." (PMID 41286463, 2026). "Here, only the APOE region is strongly associated with delirium; thus many colocalization signals in other parts of the genome may be missed." (PMID 41286463, 2026). "There are conflicting reports regarding the genetic association of APOE with delirium." (PMID 37159618, 2023). "Plasma APOE levels were also shown to be a risk factor for postoperative delirium in this study." (PMID 36483978, 2022). "We found that smoking, orthostatic hypotension, preoperative MRI indicating silent brain ischemia or infarction, taking MAOBIs, abnormal HAMA score, and abnormal plasma APOE level were independent risk factors for delirium after DBS under general anesthesia in PD patients." (PMID 36483978, 2022). "APOE ε4 status may therefore be a useful addition to estimating risk of developing delirium, especially in designing intervention trials." (PMID 30770424, 2019). "Even so, some studies question the association of APOE ε4 with delirium." (PMID 26106326, 2015). "Also important for this study are data that indicate a relationship between presence of the apolipoprotein E (ApoE) *E4 allele and delirium severity and duration." (PMID 21569370, 2011). "Both delirium and dementia are conditions of reduced cognitive reserve and have common risk factors: a lifetime of low engagement in complex mental activities and presence of the ApoE *E4 allele." (PMID 21569370, 2011). "It has been suggested that interactions between APOE-ε4 and inflammation-related proteins can drive delirium development." (PMID 41286463, 2026). "The Apolipoprotein E (APOE) gene, specifically its ε4 haplotype, is the most intensively studied gene, though clear conclusions on its relationship with delirium remain lacking." (PMID 41286463, 2026).
delirium (continued). "Combining proteins, APOE-ε4 status and demographics significantly improved incident delirium prediction compared to demographics alone." (PMID 41286463, 2026). "The findings suggest that APOE-ε4 confers vulnerability to adverse acute brain changes induced by triggers of delirium." (PMID 41286463, 2026). "Additional indicators of neuronal injury, such as S100β, APOE, cortisol, and NSE, have been associated with the onset of delirium post-anesthesia and major surgical procedures." (PMID 40092071, 2025). "A recent study demonstrated the interaction between gene Apolipoprotein E (a predisposing factor) and postoperative CRP (a protein and precipitating factor) on postoperative delirium." (PMID 36212043, 2022). "The association between the postoperative plasma concentration of CRP and the incidence, duration, and severity of postoperative delirium can be modified by the apolipoprotein E (APOE) 4 genotype and the catechol-O-methyltransferase (COMT) genotype." (PMID 36212043, 2022). "Many studies have shown that the APOE ε4 genotype significantly correlates with postoperative delirium." (PMID 36483978, 2022). "Risk factors for delirium included atypical parkinsonism, higher age at diagnosis in PD, lower baseline MMSE, and the presence of the APOE ε4 allele and the H1/H1 MAPT haplotype." (PMID 34635668, 2021). "Another article summarizing the known biomarkers for delirium notes on the inconsistencies in the outcomes of APOE E4 studies." (PMID 24795632, 2014). "We found that APOE-ε4 exerts a significant direct effect on delirium in a dose-dependent way: OR direct effect (0vs1) 1.14, 95% CI 1.08–1.2; P = 4.5 × 10−7; for one APOE-ε4 copy, and OR direct effect (0vs2) 1.29, 95% CI 1.15–1.45; P = 1.7 × 10−5 for two APOE-ε4 copies." (PMID 41286463, 2026). "We still observed a marginally better prediction of incident delirium on the test set using APOE-ε4 and the 14 stability-selected proteins on top of demographic factors (AUC from 0.758 to 0.79, P = 0.13; PR-AUC from 0.033 to 0.036), although now with a nonsignificant AUC improvement." (PMID 41286463, 2026). "The APOE protein had a negative effect on incident delirium risk, meaning that higher plasma levels of the protein are associated with reduced future risk." (PMID 41286463, 2026). "Smoking, orthostatic hypotension, preoperative MRI indicating silent brain ischemia or infarction, taking MAOBIs, abnormal HAMA score, and abnormal plasma APOE levels are independent predictors of delirium development after STN-DBS under general anesthesia in patients with PD." (PMID 36483978, 2022). "Moreover, candidate gene association studies on delirium have shown that apolipoprotein E, catechol-O-methyltransferase (COMT), and dopamine-signaling genes such as dopamine receptor 2 are related to the risk of delirium." (PMID 33086708, 2020). "Postoperative delirium and cognitive dysfunction may have common contributing factors and biomarkers such as apolipoprotein E isoforms, cortisol signaling, pro-inflammatory cytokines, neurodegenerative marker S100B, copeptin and 6-sulfatoxymelatonin levels." (PMID 26106326, 2015). "Genetic variations in the apolipoprotein E have been studied in relation to delirium." (PMID 24795632, 2014). "Besides the standard laboratory parameters several studies have examined other biomarkers and their effects on developing a POD e.g. independent studies have detected an increase in apolipoprotein E ε4 in patients with delirium, which appears to be a promising approach in the detection of POD." (PMID 39112758, 2024). "Moreover, APOE, whether below or above the normal level, was related to the occurrence of postoperative delirium." (PMID 36483978, 2022). "With regard to delirium, protein expression of apolipoproteins including CLU and APOE were previously found to be downregulated in the CSF of people with delirium compared to those with mild AD63." (PMID 41286463, 2026).
delirium (continued). "Ancestry-dependent APOE-ε4 genetic effects on delirium have not been systematically assessed previously." (PMID 41286463, 2026). "CSF levels of β-42 amyloid, total tau, and phospho-tau protein and apolipoprotein E were not routinely measured, such as in some other studies, but studies of these AD biomarkers in delirium revealed mixed results." (PMID 37367096, 2023). "Severe adverse ARIA incidents such as delirium, deterioration in memory, and seizures were infrequent, with similar occurrence rates regardless of the individual’s APOE ε4 genotype, at 1.5% in the EMERGE trial and 1.4% in the ENGAGE trial." (PMID 38258071, 2023). "Our results suggested that if APOE genotyping is not available, postoperative delirium can be predicted by simply measuring the level of total plasma APOE protein." (PMID 36483978, 2022). "The study revealed that the likelihood of delirium recovery may be influenced by lower levels of IGF-1 and the lack of the APOE-e4 genotype among female patients." (PMID 39700095, 2024).
periodontitis (36 papers, 2011 to 2025). An acute or chronic inflammatory process that affects the tissues that surround and support the teeth. "Elevated trimethylamine N-oxide (TMAO) was found in the serum of severe periodontitis patients and ApoE-/- mice with experimental periodontitis, causing gut dysbiosis and impaired endothelial function." (PMID 41552724, 2025). "During the inflammatory cell infiltration associated with chronic apical periodontitis, the macrophage subpopulation APOE-Macro became more predominant." (PMID 40909264, 2025). "Our previous findings demonstrated that the local gingival delivery of Pg LPS induced periodontitis and alveolar bone loss in Apolipoprotein E (ApoE)-deficient mice, accompanied by elevated levels of local and systemic proinflammatory cytokines." (PMID 38892314, 2024). "GV1001 notably reduced the severity of ligature-induced periodontitis by inhibiting gingival and systemic inflammation, alveolar bone loss, and vascular inflammation in WT and ApoE-deficient mice." (PMID 37628753, 2023). "Like the WT mice, the ligature-induced severe alveolar bone loss, a hallmark of periodontitis, was also examined in the ApoE-deficient mice when analyzed with μCT." (PMID 37628753, 2023). "Notably, ligature-induced periodontitis, one of the most common methods for inducing periodontitis, accelerated the formation of atherosclerotic plaque in hyperlipidemic apolipoprotein E-deficient (Apoenull) mice." (PMID 39515611, 2024). "As GV1001 has been reported to demonstrate antioxidant and anti-inflammatory activities, we investigated the effect of GV1001 on the severity of ligature-induced periodontitis and vascular inflammation in wild-type (WT) mice and the degree of lipid deposition in ApoE-deficient mice, respectively." (PMID 37628753, 2023). "Moreover, APOE—in particular, its isoform 4—was recently proposed to increase the risk of periodontitis, and APOE-2 allele is associated with higher prevalence of sporadic PD." (PMID 33238395, 2020). "Periodontitis caused by P gingivalis oral inoculation enhanced (p < 0.05) the maximal response to phenylephrine in all groups when compared to the respective control group in both C57 (Pg; 92 ± 6 versus Ct: 79 ± 3 mmHg) and ApoE (Pg: 119 ± 7 versus Ct: 98 ± 5 mmHg) groups." (PMID 21586133, 2011). "Our study evaluates the effect of photobiomodulation (PBM) on experimental ligation-induced periodontitis in hypercholesterolemic mice (ApoE knockout)." (PMID 37817126, 2023). "We observed higher levels of plasma cholesterol in ApoE mice with untreated periodontitis than in those that received PBM treatment." (PMID 37817126, 2023). "In this study, P. gingivalis was used to generate an experimental periodontitis model in ApoE−/− mice." (PMID 35118014, 2021). "The results showed that oral lavage of P. gingivalis and S. gordonii for 4 weeks, initiated periodontitis in ApoE-/- mice, similar to the human situation." (PMID 34294791, 2021). "Our research discovered that experimental periodontitis in ApoE−/− mice induced gut dysbiosis and an increase in TMAO." (PMID 35118014, 2021). "Non-surgical periodontal treatment had the trend to normalize the gut microbiota and improved the intestinal mucosal barrier impaired by periodontitis in apoE−/− mice." (PMID 33072621, 2020). "To investigate the effect of periodontitis on atherogenesis, we induced periodontitis in ApoE−/− fed a high fat diet (HFD) by placing silk-ligatures around the maxillary second molars." (PMID 31257363, 2019). "The apolipoprotein E knockout (ApoE−/−) mouse harbours wtAPP in which periodontitis is induced following an oral P. gingivalis mono-infection." (PMID 30728914, 2019). "Since ApoE-deficient mice show hyperlipidemic and systemic proinflammatory properties, we used WT mice to minimize the effect of the genetic and systemic factors in investigating the effect of GV1001 on ligature-induced periodontitis." (PMID 37628753, 2023).
periodontitis (continued). "We chose the ApoE knockout mouse model, an animal model that presents high plasma cholesterol levels and develops atheromatous lesions very similar to those in humans, to evaluate the systemic effects of periodontitis and PBM." (PMID 37817126, 2023). "Ligature-induced periodontitis significantly increased the level of triglycerides (TG) in apoE−/− mice (p < 0.05), whereas removing the causal ligature decreased TG level in periodontitis mice; and SRP further improved TG level in the plasma of apoE−/− mice (p < 0.05)." (PMID 27386384, 2016). "A number of these genes were also significantly increased in aging and periodontitis tissues (e.g., ANXA1, HMGB1, S100A8, S100A9, APOE/ß2-GPI, LTF, TSLP)." (PMID 38098978, 2023). "In our study, SERPINA1 was the core gene in PPI and correlated with seven ERS-related genes including ERLEC1, VWF, EDEM2, DERL3, APOE, IL6, and CXCL8, suggesting that SERPINA1 may play an essential role in the pathological process of periodontitis." (PMID 36072904, 2022). "Apolipoprotein E (ApoE) knockout mice fed a high-fat diet were subjected to periodontitis by ligation of silk ligature with or without P. gingivalis LPS injection at the ligated sites." (PMID 34445604, 2021). "Periodontitis and non-surgical periodontal treatment altered gut microbial function of apoE−/− mice." (PMID 33072621, 2020). "Apolipoprotein E−/−(ApoE−/−) mice were ligatured to induced periodontitis and non-surgical periodontal treatment was performed for half of them after 4 weeks of ligation." (PMID 33072621, 2020). "Additionally, more studies to evaluate the long-lasting systemic photobiomodulation effects need to be conducted, and finally, it’s worth noting that an ApoE knockout mouse model used in this study may not fully capture all the nuances of a hypercholesterolemic individual with periodontitis." (PMID 37817126, 2023).